GOLT1B (golgi transport 1B)
Diseases named in the same sentence as GOLT1B in open-access papers (continued):
Sharing a sentence is not in itself a finding about the gene and the disease.
cancer (7 papers, 2021 to 2025). A tumor composed of atypical neoplastic, often pleomorphic cells that invade other tissues. "We found that the mRNA expression of GOLT1B was upregulated in most cancer tissues and was associated with a poor prognosis of multiple cancers." (PMID 38130634, 2023). "We further explored the association between genetic alterations in GOLT1B and the clinical survival prognosis of pan-cancer cases." (PMID 38130634, 2023). "The associations between the immune infiltration level of CD4+ cells and cancer-associated fibroblasts with GOLT1B expression were explored using TIMER2." (PMID 38130634, 2023). "Notably, Golgi transport protein 1B (GOLT1B) was upregulated in most cancer tissues and was associated with immune cell infiltration, particularly the infiltration of T helper type 2 (Th2) cells." (PMID 40519935, 2025). "High expression levels of GOLT1B have been associated with poor prognosis of most cancers." (PMID 38130634, 2023). "In addition, the heatmap of all algorithms showed a positive correlation between GOLT1B expression and the estimated infiltration value of cancer-associated fibroblasts for most TCGA tumors, including COAD, HNSC, HNSC-HPV, and PAAD." (PMID 38130634, 2023). "GO/KEGG pathway analyses revealed that Golgi vesicle transport and ER to Golgi vesicle-mediated transport might be associated with the effect of GOLT1B on cancer pathogenesis." (PMID 38130634, 2023). "Meanwhile, data from xCell revealed that the level of CD4+ memory T cell subset infiltration was positively associated with GOLT1B expression in pan-cancer analyses, while the level of central and effector memory subset infiltration was negatively associated with GOLT1B expression." (PMID 38130634, 2023). "Additionally, the high expression of GOLT1B was also found to be positively associated with the infiltration of cancer-associated fibroblasts (CAFs), which were key components of the TME with diverse functions." (PMID 38130634, 2023). "In summary, the present pan-cancer analysis, for the first time, offered a comprehensive understanding of the oncogenic role of GOLT1B across different cancers, demonstrating the potential of GOLT1B as a diagnostic biomarker and a target for cancer immunotherapy." (PMID 38130634, 2023). "Copy number amplification was the primary type of GOLT1B genetic alterations, which was related to the prognosis of pan-cancer cases." (PMID 38130634, 2023). "Genetic alteration by amplification supports the prognostic potential of GOLT1B, and large cohort validations with complete clinical data across different cancers are warranted." (PMID 38130634, 2023). "The potential relationship between the different levels of immune infiltration and GOLT1B genetic alterations in diverse cancer types in TCGA was investigated using the TIMER2." (PMID 38130634, 2023). "Taken together, our results further confirmed the involvement of GOLT1B with the infiltration of different immune cells in cancers." (PMID 38130634, 2023). "Copy number amplification was the primary type of GOLT1B genetic alterations, with an alteration frequency of approximately 1.9% in pan-cancer types." (PMID 38130634, 2023). "Further studies are warranted to elucidate the specific regulatory mechanisms of GOLT1B in carcinogenesis to improve the efficacy of cancer diagnosis and the diverse application of immunotherapy." (PMID 38130634, 2023). "Results of the CIBERSORT and CIBERSORT-ABS algorithms showed that there were positive correlations between activated CD4+ memory T cells, resting subsets, and GOLT1B expression in most cancer types such as BRCA and SKCM." (PMID 38130634, 2023). "In our study, the differential status of GOLT1B promoter methylation across diverse cancers was determined." (PMID 38130634, 2023). "Copy number amplification was identified as the primary type of GOLT1B genetic alteration related to the prognosis of pan-cancer cases." (PMID 38130634, 2023).
cancer (continued). "The correlation between GOLT1B mRNA expression and the pathological stage of cancers including ACC, BLCA, LUAD, OV, and UCS was obtained (P < 0.05)." (PMID 38130634, 2023). "The correlation between GOLT1B expression levels and prognosis in different cancers was analyzed by using GEPIA2." (PMID 38130634, 2023). "Our study provides insights into the application of GOLT1B as a potential prognostic biomarker in several cancers in the context of immuno-oncology and contributes to the development of GOLT1B-targeting therapeutic strategies." (PMID 38130634, 2023). "There was also a positive correlation between GOLT1B genetic alterations and CD4+ T lymphocytes, especially the Th2 subset, as well as between GOLT1B expression and the estimated infiltration value of cancer-associated fibroblasts." (PMID 38130634, 2023). "Moreover, GOLT1B was positively correlated with the Th2 subset of CD4+ cells and cancer-associated fibroblasts, playing a specific role in immune infiltration." (PMID 38130634, 2023). "GOLT1B mRNA expression levels in different types of cancer were analyzed in Oncomine." (PMID 38130634, 2023). "There were different levels of GOLT1B promoter methylation across cancer types." (PMID 38130634, 2023). "However, our pan-cancer analysis also showed that GOLT1B overexpression contributed negatively to prognosis in patients with ESCA and PAAD." (PMID 38130634, 2023). "There was a significant correlation between the CD4+ subsets of T cells and GOLT1B expression in TGCT and OV, two cancer types with the highest alteration frequency of copy number of sCNA." (PMID 38130634, 2023). "Co-culture of GOLT1B-overexpresed CRC cells with Jurkat cells significantly induced T cells apoptosis, which might further promote cancer cell the migration and invasion." (PMID 34059062, 2021).
GOLT1B also shares sentences with these, for which no sentence is quoted: adrenal cortical carcinoma (2 papers); cholangiocarcinoma (1); clear cell carcinoma of the kidney (1); endometrial cancer (1); esophageal carcinoma (1); glioblastoma (1); hepatitis C (1); invasive breast carcinoma (1); ovarian serous cystadenocarcinoma (1); sarcoma (1); seminoma (1); skin cutaneous melanoma (1); squamous cell carcinoma of the head and neck (1); thymoma (1); tumors of the reproductive system (1); uterine carcinosarcoma (1).